GUCY2F (guanylate cyclase 2F, retinal)
Description:
Responsible for the synthesis of cyclic GMP (cGMP) in rods and cones of photoreceptors. Plays an essential role in phototransduction, by mediating cGMP replenishment (By similarity). May also participate in the trafficking of membrane-associated proteins to the photoreceptor outer segment membrane (By similarity).
Synonyms: RETGC-2; GC-F; ROS-GC2; GUC2F; GUC2DL; CYGF
Tractability: Small molecule: it belongs to a druggable protein family. Antibody: its Gene Ontology location is reachable by antibodies, with high confidence; UniProt predicts a signal peptide or a membrane-spanning region.
Gene: Protein-coding gene on chromosome X (109,372,906 to 109,482,086, reverse strand). Ensembl gene ENSG00000101890.
Subcellular location: Photoreceptor outer segment membrane
Pathways (Reactome):
Sensory Perception: Inactivation, recovery and regulation of the phototransduction cascade
Gene Ontology:
Molecular function: guanylate cyclase activity; peptide receptor activity; signaling receptor activity; ATP binding; identical protein binding; phosphorus-oxygen lyase activity; protein heterodimerization activity; protein kinase activity
Biological process: cGMP biosynthetic process; receptor guanylyl cyclase signaling pathway; regulation of opsin-mediated signaling pathway; visual perception; cGMP metabolic process; cyclic nucleotide biosynthetic process; detection of light stimulus involved in visual perception; intracellular signal transduction
Cellular component: nuclear outer membrane; photoreceptor disc membrane; photoreceptor outer segment membrane; plasma membrane; rod photoreceptor outer segment; rod photoreceptor disc membrane
Homologues: Orthologues: chimpanzee GUCY2F (99% identical), macaque GUCY2F (97% identical), rabbit GUCY2F (92% identical), dog GUCY2F (91% identical), guinea pig GUCY2F (90% identical), mouse Gucy2f (90% identical), rat Gucy2f (90% identical), tropical clawed frog gucy2f (69% identical). Paralogues in human: GUCY2D (50% identical), NPR2 (32% identical), NPR1 (31% identical), GUCY2C (28% identical), ADCY6 (17% identical), ADCY5 (17% identical), ADCY2 (16% identical), ADCY7 (16% identical), ADCY4 (16% identical), ADCY8 (16% identical), ADCY3 (15% identical), GUCY1A2 (15% identical), and 5 more.
Diseases named in the same sentence as GUCY2F in open-access papers:
GUCY2F is named in the same sentence as 2 diseases in open-access papers, as found by Europe PMC text mining. Sharing a sentence is not in itself a finding about the gene and the disease. The quoted sentences say what the papers report.
glaucoma (1 paper, 2021). Increased pressure in the eyeball due to obstruction of the outflow of aqueous humor. "These 13 glaucoma-associated genes can be divided into three functional groups: phototransduction-related genes (GNGT1, OPN1SW, PDE6A, PDC, CRX, CNGB1, GUCY2F), glutamate receptor (GR) genes (GRIN2B, GRIK3, GRIK4), and 5-hydroxytryptamine receptor (HTR) genes (HTR1A, HTR1E, HTR7)." (PMID 33874942, 2021).
retinal disease (1 paper, 2025). "A majority of the significantly differentially expressed (FC > 2, FDR < 1%) genes show an increase in expression with higher glucose; these include genes involved in retina development (Neurod1, Casz1, and Crxos) or those associated with retinal disease (Impg1/2, Gucy2f, Mpp4, Arl6, and Rp1)." (PMID 40568109, 2025).